CCL2 (C-C motif chemokine ligand 2)
Diseases named in the same sentence as CCL2 in open-access papers (continued):
Sharing a sentence is not in itself a finding about the gene and the disease.
Azoospermia (1 paper, 2023). Absence of any measurable level of sperm,whereby spermatozoa cannot be observed even after centrifugation of the semen pellet. "The present study revealed CCL2-relevant changes in the testicular immune microenvironment in spermatogenic dysfunction, providing new evidence for the role of immunological factors in azoospermia." (PMID 37221631, 2023).
basophilic leukemia (1 paper, 2016). "Moreover, CCL3 synergistically enhanced FcεRI-mediated degranulation and the production of CCL2, which is a chemoattractant for T cells and eosinophils in bone marrow-derived murine mast cells and the rat basophilic leukemia 2H3 cell line." (PMID 27829417, 2016).
Becker muscular dystrophy (1 paper, 2021). Becker muscular dystrophy (BMD) is a neuromuscular disease characterized by progressive muscle wasting and weakness due to degeneration of skeletal, smooth and cardiac muscle. "In this study, we used a highly specific and reproducible MSD ELISA assay to examine the levels of the three chemokines (CXCL10, CCL2, and CCL18) in serum and muscle samples collected from DMD patients, Becker muscular dystrophy (BMD) patients, and age-matched healthy controls." (PMID 34440571, 2021).
bladder disorders (1 paper, 2017). "Chemokines are known contributors to symptoms of bladder disorders, and Perters found remarkably reduced levels of chemokines CXCL-1, CXCL-10, and CCL-2 in patients who had received sacral neuromodulation therapy for BPS/IC." (PMID 28106785, 2017).
bubonic plague (1 paper, 2012). A plague in which the bacteria have infected the lymphatic system. "A recent study of the systemic phase of bubonic plague due to fully virulent Y. pestis CO92 showed high levels of the PMN maturation factor G-CSF, chemokines CXCL1 and CCL2, as well as cytokines IL-6 and Il-1α in plasma." (PMID 23248776, 2012).
Candida systemic infection (1 paper, 2024). "IFN-I signaling controls the recruitment of inflammatory myeloid cells, including Ly6Chi monocytes and neutrophils, to infected mouse kidneys by driving the expression of the chemokines CCL2 and CXCL1, which aggravates renal immunopathology during Candida systemic infection." (PMID 38166150, 2024).
carditis (1 paper, 2012). "Nevertheless, CCL2 has been demonstrated to enhance migration of T cells across B. burgdorferi-stimulated HUVEC, and B. burgdorferi -specific CD4+ T cells were shown to play important roles in the severity of murine Lyme arthritis and carditis." (PMID 23024745, 2012).
cervical adenocarcinoma (1 paper, 2020). An adenocarcinoma arising from the cervical epithelium. "Meanwhile, serum CCL2 showed a notable raise especially in cervical adenocarcinoma." (PMID 32064233, 2020).
cholangitis (1 paper, 2018). An acute or chronic inflammatory process affecting the biliary tract. "Therapeutic blockade of IL-15 in obese mice with cholangitis resulted in attenuated histological damage, lower numbers of infiltrating neutrophils and CD8+ T cells and reduced levels of proinflammatory cytokines and chemokines including IL-13, IL-17, C-GSF, CCL2, CCL3 and CXCL10." (PMID 29449577, 2018).
chronic allograft nephropathy (1 paper, 2021). "The intragraft expression of CCL2 (MCP-1) mRNA has been already described in patients with chronic allograft nephropathy." (PMID 33776571, 2021).
chronic cervicitis (1 paper, 2024). Chronic inflammation of the cervix. "We used a set of patient-derived precancerous (n = 32) and noncancerous (chronic cervicitis; n = 10) tissue samples to investigate the gene expression of several OIS (LMNB1, CDKN2A, CDKN2B, and CDKN1A), and SASP (IL1A, CCL2, TGFB1, CXCL8, and MMP9) biomarkers using qRT-PCR." (PMID 39727946, 2024).
chronic headache (1 paper, 2024). "In a mouse model of chronic migraine, we have found that the peripheral C-C motif ligand 2 (CCL2), C-C motif chemokine receptor 2 (CCR2) and CGRP signaling pathways interact with each other and play critical roles in the development of chronic headache-related behavioral and cellular sensitization." (PMID 39528947, 2024).
craniopharyngioma (1 paper, 2019). A benign, partly cystic, epithelial tumor of the sellar region, presumably derived from Rathke pouch epithelium. "Cytokine array data from human craniopharyngiomas identified CCL2 and IL-8 as the most secreted cytokines in plasma, primary culture supernatants, cell and tissue lysates." (PMID 31703742, 2019).
Crush Syndrome (1 paper, 2022). Severe systemic manifestation of trauma and ischemia involving soft tissues, principally skeletal muscle, due to prolonged severe crushing. "The expression levels of inflammatory cytokines and chemokines (e.g., TNFα, IL-6, CXCL1, CXCL2, CXCR2, CCL2) in crush syndrome were significantly suppressed in TPEN-treated group." (PMID 36114355, 2022).
diabetic eye disease (1 paper, 2024). A group of disorders affecting the eye in patients with diabetes mellitus. "Network meta-analysis revealed that CCL8, CCL2, CXCL8 and CXCL10 may be involved in key pathophysiological process of diabetic eye disease." (PMID 38790059, 2024). "Our study suggests that CCL2 and CXCL8 may play key roles in pathogenesis of diabetic eye disease." (PMID 38790059, 2024). "Specifically, this network meta-analysis indicated that CC chemokines (CCL8 and CCL2) and CXC chemokines (CXCL8 and CXCL10) may discriminate between those with and without diabetic eye disease." (PMID 38790059, 2024).
dissection (1 paper, 2019). The separation and isolation of tissues for surgical purposes, or for the analysis or study of their structures. "We chose CCL2 since its involvement in aortic dissection has been observed in multiple reports." (PMID 31341173, 2019).
endometrial stromal sarcoma (1 paper, 2022). "In a study, the human endometrial stromal sarcoma cell line Mami constitutively produces CCL2 in vitro, and interleukin-1β, tumor necrosis factor α, and lipopolysaccharide-induced the expression of CCL2 in MaMi cells." (PMID 36403055, 2022).
endometrial tumor (1 paper, 2025). "Other produced cytokines in the endometrial tumor environment include IL-6, IL-8, monocyte chemotactic protein-1 (MCP-1 or CCL2), chemokine ligand 5 (CCL5 or RANTES) and vascular endothelial growth factor (VEGF)." (PMID 41228294, 2025).
erysipelas (1 paper, 2017). An infection of the upper layers of the skin caused by species of streptococcus. "The cytokine values of CCL2 were observed to be significantly lower in erysipelas patients with the C/C genotype of CAT C262T than in the individual in the control group with the C/C genotype." (PMID 28512644, 2017).
esophageal tumors (1 paper, 2020). "It was worth noting that chemokine (C-C motif) ligand 2 (CCL2) as the leading chemokine was prominently over-expressed in esophageal tumors." (PMID 32103760, 2020).
fungal keratitis (1 paper, 2015). "Our experiment confirmed that Dectin-1 in early period of innate immune in rat fungal keratitis can work through IL-1β, IL-6, CCL2, CXCL1, CXCL2 to recruit neutrophils and macrophages to participate anti-fungal immunity." (PMID 26427623, 2015). "Dectin-1 in early period of innate immune responses in rat fungal keratitis might work through IL-1β, IL-6, CCL2, CXCL1, CXCL2 to recruit neutrophils and macrophages to participate anti-fungal immunity." (PMID 26427623, 2015).
G6PD deficiency (1 paper, 2024). An X-linked genetic condition caused by alterations in the gene G6PD that result in moderately to severely decreased activity levels of the enzyme glucose-6-phosphate dehydrogenase. "In this context, other studies have reported that overexpression of G6PD evokes an inflammatory response in the adipose tissue of diabetic mice, and conversely, G6PD deficiency reduces diet-induced CCL2 and inflammation of adipose tissue in mice." (PMID 38876306, 2024).
gonococcal infection (1 paper, 2018). "Fallopian tube explants release cytokines and chemokines capable of recruiting macrophages during gonococcal infection, such as MCP-1 (CCL2) and MIP-1β (CCL4)." (PMID 30524442, 2018).
Graves disease (1 paper, 2025). Graves' disease is an autoimmune disorder that leads to overactivity of the thyroid gland (hyperthyroidism).It is caused by an abnormal immune system response that causes the thyroid gland to produce too much thyroid hormones. "The shift from Th1 to Th2 immune response, marked by CCL2 and CCL22, is observed in advanced stages of PsA and Graves’ disease." (PMID 40863211, 2025).
hemangiosarcoma (1 paper, 2023). "In samples of canine tumors, pulmonary metastases from hemangiosarcoma were shown to have greater numbers of monocytes compared to metastases from other tumor types, as well as significantly higher CCL2 production, a monocyte chemoattractant protein (also called MCP-1)." (PMID 37090720, 2023).
hemoglobinopathy (1 paper, 2020). "Thus, our results suggest that chemokines CXCL10 and CCL2 and cytokines, TNF-α, IL-8, and IL-6 may contribute to the overall pro-inflammatory response and could be utilized for predicting the severity of Plasmodium infection or a hemoglobinopathy." (PMID 33424841, 2020).
hemophilia B (1 paper, 2020). Hemophilia B is a form of hemophilia characterized by spontaneous or prolonged hemorrhages due to factor IX deficiency. "INS regulates vascularization; APOH, F2, and ICAM regulate platelet activation and adhesion; AGT regulates blood vessel contraction; TNF and CCL2 regulate blood chemokine in circulation; F9 regulates onset Hemophilia B, and PON1 inhibits onset cardiovascular disease." (PMID 32753925, 2020).
hepatitis D (1 paper, 2025). "Other analyses of cytokine/chemokine profiles within cohorts with hepatitis D identified some cytokines and chemokines (e.g. CCL2 and CCL27) to be decreased in patients with high hepatitis D viraemia compared with patients with low viraemia." (PMID 39980752, 2025).
hereditary haemorrhagic telangiectasia (1 paper, 2017). "Also down‐regulated are ACVRL1—mutations in which cause vessel malformations in hereditary haemorrhagic telangiectasia 46—endothelin 1 (EDN1), which encodes vasoconstrictive peptides, and CCL2, which has chemotactic activity for monocytes and basophils." (PMID 28631889, 2017).
herpetic keratitis (1 paper, 2024). "Another lab reported that mice exposed to polluted air developed a severe form of herpetic keratitis with increased corneal opacity, neovascularization, and production of TNF-α, IL-1β, IFN-γ, and CCL2." (PMID 38928968, 2024).
hyperreactivity (1 paper, 2019). "Accordingly, targeted disruption and antibody-mediated neutralization of CCL2 reduces airway allergic inflammation and airway hyperreactivity in allergen-challenged mice." (PMID 30654796, 2019).
Hypofibrinogenemia (1 paper, 2020). Decreased concentration of fibrinogen in the blood. "The correlation network analyses between the molecules evaluated in the present study show that, in the group of patients with hypofibrinogenemia, it was possible to observe a predominance of a chemoattractive profile, with correlations between chemokines CXCL-8, CXCL-9, CCL-2, and CXCL-10." (PMID 32973773, 2020).
idiopathic interstitial pneumonia (1 paper, 2024). A class of diffuse lung diseases that typically affect the pulmonary interstitium, although some also have a component affecting the airways (for instance, Cryptogenic organizing pneumonitis). "While combined detection of CCL2, KL-6, and CXCL13 improves diagnostic accuracy for idiopathic interstitial pneumonia (IIP), it does not effectively differentiate among lung fibrosis diseases." (PMID 39850880, 2024).
inflammatory diarrhea (1 paper, 2025). An diarrhea (disease) involving a pathogenic inflammatory response in the intestinal mucosa. "Notably, the combination of Machiline and CCL2 exhibited a binding energy that was below −5.0 kcal/mol, suggesting that the active constituents of Lotus Leaf possess a relatively stable binding affinity with targets associated with porcine inflammatory diarrhea." (PMID 40699713, 2025).
intestinal infection (1 paper, 2022). "Our study revealed the alternative function of epithelial-derived CCL2 in stimulating intestinal IELs migration behavior in response to intestinal infection." (PMID 35318455, 2022).
intestinal polyp (1 paper, 2016). Discrete abnormal tissue masses that protrude into the lumen of the intestine. "Intestinal polyp formation in the ApcMin/+ mouse coincides with increased pro-inflammatory cytokines such as TNF, IL1B, IL6, and CCL2 (MCP-1), likely driven by constitutively activated NFKB1." (PMID 27612418, 2016).
irritant contact dermatitis (1 paper, 2024). "Proinflammatory cytokines such as CCL2 have also been shown to be potentially involved in psoriatic skin inflammation and irritant contact dermatitis." (PMID 38379420, 2024).
lentivirus infection (1 paper, 2022). Virus diseases caused by the Lentivirus genus. "To further confirm the protumoral role of CCL2, we depleted CCL2 in MDA-MB-231 and 4T1 cells by lentivirus infection and performed in vivo tumor growth and lung metastasis assay." (PMID 36038549, 2022).
malformations of the central nervous system (1 paper, 2024). "Furthermore, higher levels of CCL2/MCP-1 and TNFα expression have been observed in ZIKV-infected mothers who gave birth to infants with congenital malformations of the central nervous system than in pregnant women whose fetuses were normal." (PMID 38839691, 2024).
melasma (1 paper, 2022). "The CCL2 expression profile in fibroblasts can induce the darker focal phenotype of melasma." (PMID 35840442, 2022). "TheWNT3A, EDN3, ESR2, PTG2, MMP1, and SOD2 genes were up-regulated, whereas the COL4A1, CSF2, DKK3, COL7A1, TIMP4, CCL2, and CDH11 genes were down-regulated in melasma skin fibroblasts when compared to the ones from adjacent healthy skin." (PMID 35840442, 2022).
meningeal tumor (1 paper, 2019). "Correlation of Neudesin concentration with the previously tested proteins: IL-8, CCL2, sICAM-1, Nogo-A showed a strong positive relationship between serum Neudesin concentrations and CSF Nogo-A levels in the meningeal tumor subgroup." (PMID 30953468, 2019).
metastatic colorectal cancer (1 paper, 2017). "We have shown that carcinoembryonic antigen cell adhesion molecule 1 long isoform (CEACAM1-L) expression in MC38 metastatic colorectal cancer (CRC) cells results in liver metastasis inhibition via CCL2 and STAT3 signaling." (PMID 29262644, 2017).
Middle East respiratory syndrome (1 paper, 2022). A viral respiratory infection that is caused by the MERS coronavirus (MERS-CoV), which most often manifests with moderate to severe respiratory symptoms, including productive cough and shortness of breath, which can progress to pneumonia and acute respiratory distress syndrome. "This includes the pro-inflammatory cytokines such as interleukin (IL)-1, IL-6 and tumor necrosis factor (TNF)-α, as well as the inflammatory chemokines CCL-2 and CXCL-10, which have previously been seen in other coronavirus infections such as Middle East respiratory syndrome (MERS)." (PMID 35054471, 2022).
Mm (1 paper, 2017). "At 1 hr post infection, when the recruited phagocytes comprise almost entirely resident macrophages, ccl2-positive phagocytes were present, but only following wild-type Mm infection and not PGL-deficient Mm infection." (PMID 28844797, 2017).
Mycoplasma pneumoniae pneumonia (1 paper, 2023). Interstitial pneumonia caused by extensive infection of the lungs (lung) and bronchi, particularly the lower lobes of the lungs, by mycoplasma pneumoniae in humans. "There are relatively few studies investigating C-C motif chemokine ligand 2 (CCL2) level in bronchoalveolar lavage fluid (BALF) in children with Mycoplasma pneumoniae pneumonia (MPP), and the relationship between CCL2 level in BALF and refractory mycoplasma pneumoniae pneumonia (RMPP) is unclear." (PMID 37740208, 2023).
Myelopathy (1 paper, 2026). Myelopathy is an descriptive term, referring to pathology leading to a neurologic deficit related to the spinal cord. "We discuss current evidence of CAR-T-associated myelopathy, its proposed inflammatory and immune-trafficking mechanisms, and the potential contribution of interleukins and chemokines such as IL-1, IL-6, IL-18, CCL-2 and CXCL10 signaling to spinal cord injury." (PMID 41993175, 2026).
Niemann-Pick type C disease (1 paper, 2025). "Previous studies on the impact of CCL2 on the proliferative potential and neurogenesis of endogenous NSC in a mouse model of Niemann-Pick type C disease showed a significant increase in the ability for self-renewal, proliferation, and differentiation of neurons." (PMID 40162096, 2025).
Nocardia infection (1 paper, 2022). "Interestingly, the expression of CCL2 was downregulated during lung infection caused by N. farcinica, which supported the differential regulation and functions of chemokines during Nocardia infection." (PMID 36352407, 2022).
occupational dermatitis (1 paper, 2021). Contact dermatitis associated with allergens or irritants found in the workplace. "In nickel induced occupational dermatitis, the expression of CCL2 declines gradually 72–96 hours after nickel application, correlating with our findings using cobalt." (PMID 34086734, 2021).
ovarian serous cystadenocarcinoma (1 paper, 2022). A malignant serous cystic epithelial neoplasm arising from the ovary. "Positive correlations were found between the mRNA levels of BCL3 with some of these target genes, such as TNFAIP3/A20, CCL2, CD274, and CXCL10, in brain lower grade glioma (LGG) and ovarian serous cystadenocarcinoma (OV) samples from TCGA database." (PMID 35990614, 2022).
pancreatic neuroendocrine cancers (1 paper, 2013). "CSF-1/CSF-1R and CCL2 (MCP-1)/CCR2 signaling in murine breast and pancreatic neuroendocrine cancers induces TAM recruitment and a pro-tumorigenic M2-like phenotype." (PMID 23372702, 2013).
paroxysmal AF (1 paper, 2021). "However, when patients with paroxysmal AF and permanent AF were separately analyzed, while increase in CCL2 was observed in both subgroups, CRP was only elevated in those with the permanent condition." (PMID 33765041, 2021).
polyneuropathy (1 paper, 2025). A disease or disorder affecting more than one nerve. "In our panel, blood concentrations of CCL2, a proinflammatory chemoattractant for monocytes, were increased, as previously seen in preclinical neuropathic pain models and in patients with polyneuropathy." (PMID 39909798, 2025).
posterior uveitis (1 paper, 2007). Inflammation of the choroid as well as the retina and vitreous body. "Increased expression of CCR2 (receptors for MCP-1/CCL2) and CCR5 genes on posterior segment extracts have also been found in animal models of posterior uveitis." (PMID 17417600, 2007).
pseudoexfoliation glaucoma (1 paper, 2025). "Earlier, we showed that elevated IOPs were significantly correlated with the intracameral levels of IL-5, IL-6, IL-8, IL-10, IL-15, IL-17, and CCL2 in eyes with pseudoexfoliation glaucoma." (PMID 40353220, 2025).
pterygium (1 paper, 2018). A wedge-shaped fibrovascular lesion arising from the bulbar conjunctiva and extending to the cornea. "Of the important relevant genes in pterygium are epithelial neutrophil activating peptide 78 (CXCL5), monocyte chemotactic protein 1 (CCL2), and matrix metalloproteinases (MMPs)." (PMID 31565648, 2018).
rectal adenoma (1 paper, 2025). "Notably, a significant downregulation of CCL2 was observed in rectal adenoma (a benign lesion) with a fold change (FC) of −3.318 and a p-value of 2.82 × 10−4." (PMID 39859340, 2025).
rectal polyps (1 paper, 2021). "The rectal polyps downregulated CCL2 and CCL7 by 3.1-fold and CCL8 by 5.3-fold, while gene downregulation in the colonic polyps was absent or less substantial." (PMID 34884259, 2021).